CCND1 (cyclin D1)
Diseases named in the same sentence as CCND1 in open-access papers (continued):
Sharing a sentence is not in itself a finding about the gene and the disease.
pancreatic cancer (continued). "Mechanistic investigation demonstrated that SEMA6C acts as a tumor suppressor in pancreatic cancer by inhibiting the AKT/GSK3 signaling axis, resulting in a decrease in cyclin D1 expression and cellular proliferation." (PMID 35269749, 2022). "For instance, combination of T3 and gemcitabine was reported to down-regulate NF-Kβ activity along with NF-Kβ regulated gene products, such as cyclin D1, c-Myc, VEGF, MMP-9, and CXCR4 in pancreatic cancer." (PMID 34371830, 2021). "In addition, the cell cycle-related molecules cyclin D1 and B1 were dysregulated by treatment with heptelidic acid, suggesting that heptelidic acid induced an abnormal cell cycle, resulting in the accumulation of cell cycle-arrested cells and the subsequent apoptosis of pancreatic cancer cells." (PMID 34040123, 2021). "An IPA interaction network analysis revealed the genes CCND1, CDK1A, CDK1B, Cyclin E (also known as CCNE1), and EGFR at the interface between the gemcitabine pathway and the pancreatic cancer signaling." (PMID 33925948, 2021). "A recent paper reported that DHA promotes the cell apoptosis of PANC-1 pancreatic cancer cells by inducing DNA fragmentation, activating caspase-3, and increasing the ratio of Bax/Bcl-2 via downregulating STAT3/nuclear factor (NF)-κB/cyclin D1 signaling." (PMID 33801246, 2021). "The dysregulation of the miR-15a and miR-16-1 cluster involves multiple oncogenic phenotypes such as cell survival, proliferation, and invasion by directly targeting CCND1 (cyclin D1), WNT3A, and BCL2, evident in prostate and pancreatic cancers." (PMID 32660045, 2020). "The present paper reported that, in pancreatic cancer (PC) cells, E2F1, CCND1, CCNE1, and all members of the MCM2-7 family were downregulated after inhibition of the RPL21 expression, leading to the reduction of DNA replication." (PMID 33014855, 2020). "In pancreatic cancer cells, CDX2 inhibits cell proliferation by directly repressing cyclin D1 transcriptional activity." (PMID 30631044, 2019). "We previously demonstrated that GSK3β sustains expression of CDK4, CDK6, and cyclin D1, which results in phosphorylation-dependent inactivation of RB cell cycle regulator, in CRC and pancreatic cancer cells." (PMID 29568361, 2018). "MiR-192 overexpression diminished the expression of p21Cip1, p27Kip1, p107, p130 and retinoblastoma-1 tumor suppressor protein (Rb1) and increased the expression of cyclin D1, cyclin D2, CDK4, CDC2, and SKP-2 in both pancreatic cancer tissues and cell lines." (PMID 27240340, 2016). "Overexpression of cyclin D1/CDK4 is regulated by CEACAM6 and promotes cell proliferation in human pancreatic carcinoma." (PMID 27818681, 2016). "Our present study indicates that capsaicin disrupts the interaction of β-catenin/TCF complex in the nucleus of pancreatic cancer cells and thereby suppresses β-catenin/TCF mediated cell proliferative genes such as c-Myc and cyclin D1." (PMID 25869100, 2015). "PM inhibited p-Akt and its downstream targets Foxo-3α and cyclin D1; NF-κB (p65) and NF-κB-regulated Cox-2 and VEGF; p-mTOR and mTOR-regulated p-S6K1 and p-4E-BP1 in both pancreatic cancer cell lines." (PMID 24603988, 2014). "In MIA PaCa-2 (a pancreatic cancer cell), LOX-PP attenuated the ERK and Akt activities and decreased the levels of the NF-Kβ p65 and RelB subunits and cyclin D1, which are activated by RAS signalling." (PMID 23750284, 2013). "In all four pancreatic cancer cell lines tested, we found decreased expression of cell cycleproteins, including E2F1, Cyclin D1, Cyclin E, Cdk2, Cdk4 and Cdk6, and increased expression of p21 and p27." (PMID 23028659, 2012). "3-Cl-AHPC and AHP3 exposure on the expression of cyclin D1, β-catenin, and IGF-1R in the pancreatic cancer cells was assessed." (PMID 22570653, 2012). "3-Cl-AHPC exposure on pancreatic cancer cells decreased expression of IGF-1R, cyclin D1, and β-catenin prior to the inhibition of proliferation and the induction of apoptosis." (PMID 22570653, 2012).
pancreatic cancer (continued). "Addition of 3-Cl-AHPC downregulated β-catenin expression in pancreatic cancer cells and inhibited Wnt/β-catenin activation of transcription factor TCF/LEF and also downregulated Wnt/β-catenin pathway responsive genes cyclin D1 and c-Myc in PANC-1 cells." (PMID 22570653, 2012). "Molecular analysis of residual tumors treated with MK591 revealed reduced levels of ERK, cyclin D1 and Aurora kinase B proteins, suggesting that targeting 5-Lox by MK591 or similar agents could be a potent strategy for inhibiting pancreatic tumor growth." (PMID 38746674, 2024). "Furthermore, ZNF655 knockdown resulted in downregulation of CCND1 expression and inhibition of PI3K/AKT signaling pathway in pancreatic cancer cells." (PMID 35927248, 2022). "The median survival months for patients with pancreatic cancer and negative for the tissue expression of Cyclin-D1 was 14.00 (4.29–23.70) months." (PMID 35448172, 2022). "It was rather unexpected that the downregulation of SOX9 in all the six investigated pancreatic cancer cell lines did not significantly alter the expression of cyclin D1 (CCND1) and PCNA." (PMID 35884771, 2022). "Pancreatic tumor cell stimulation by apelin induces inhibitory phosphorylation of GSK-3, a direct downstream Akt effector, and positively regulates β-catenin, c-myc and cyclin D1 protein levels." (PMID 36142542, 2022). "Regarding the mechanism, knockdown of FN1 promotes cell apoptosis and induces cell cycle arrest by reducing the expression of cyclin D1, indicating that FN1 contributes to the development of pancreatic cancer by affecting cell apoptosis and the cell cycle in a certain manner." (PMID 34567847, 2021). "Studies have found that adiponectin can inhibit the accumulation of β - Catenin in pancreatic cancer cells by inactivating GSK-3β, thereby reducing the expression of cyclin D1 and leading to arrest of the pancreatic cancer cell cycle in G-G phase, which plays a protective role in pancreatic cancer." (PMID 34485124, 2021). "For example, in pancreatic cancer cells, lupeol induces apoptosis by decreasing the levels of p-AKT and p-ERK, as well as cell cycle arrest in the G0/G1 phase, by upregulating P21 and P27 and downregulating cyclin D1 proteins." (PMID 32571387, 2020). "In addition, forced expression of IRF2 increased the expressions of proliferation-related genes cyclin D1 and proliferating cell nuclear antigen (PCNA), suggesting that IRF2 exerted oncogenic activities in human pancreatic cancer." (PMID 30876449, 2019). "The effective role of CCND1 and MYC in 31 pancreatic cancer cell lines are assessed and emphasized." (PMID 29511477, 2017). "A decrease in cyclin D1 expression was observed in the AsPC1 cells treated with AKT and ERK1/2 inhibitors, suggesting the involvement of these pathways in the up-regulation of cyclin D1 in pancreatic cancer cells." (PMID 26556864, 2015). "STAT3 shRNA completely inhibited the expression of cyclin D1 in both pancreatic cancer cell lines in the presence or absence of EGCG." (PMID 22348037, 2012). "In contrast to CCND1 and D3, which are often differentially over-expressed in PDAC, CCND2 appears to play a role mainly in the proliferation of pancreatic islet β-cell, and its mRNA expression was infrequently detected in PDAC and pancreatic cancer cell lines." (PMID 20113529, 2010). "In addition, a study previously reported the reduction of cyclin D1 expression following therapy of pancreatic cancer cells with nonsteroidal anti‐inflammatory drugs such as sulindac, which suppress cell cycle progression." (PMID 40051490, 2025). "Furthermore, we demonstrated that miR-196a promoted pancreatic cancer proliferation through G0/G1 arrest and decreased Cyclin D1 expression and CDK4/6 expression but not apoptosis." (PMID 24504166, 2014).
pancreatic cancer (continued). "Our recent in vitro studies suggest that prolonged exposure of pancreatic cancer cells to mTOR inhibitors can promote insulin receptor substrate-PI3K interactions and paradoxically increase Akt phosphorylation and cyclin D1 expression in pancreatic cancer cells (negative feedback loop)." (PMID 20630061, 2010).
ovarian carcinoma (186 papers, 1996 to 2025). A malignant neoplasm originating from the surface ovarian epithelium. "ANXA114‐26 decreased multidrug resistance‐associated protein 1 (MRP1) expression in ovarian cancer cells through the FPR/Cyclin D1/NF‐ĸBp65 pathway." (PMID 39712859, 2025). "Ccnd1 overexpression is strongly associated with shortened progression-free survival in human ovarian carcinomas." (PMID 36430324, 2022). "A prior study has additionally revealed that cisplatin can downregulate CCND1 in human ovarian cancer epithelial cells which shares an association with delayed cell proliferation and boosted apoptosis." (PMID 35739532, 2022). "n summary, analysis based on the Oncomine database revealed that CCND1 gene was highly expressed in ovarian cancer tissue and associated with the prognosis of ovarian cancer patients." (PMID 34806539, 2021). "STAT3 knockdown with specific small interfering RNA causes a loss of cell growth and induces apoptosis in human ovarian cancer cells, consistent with down-regulation of cyclin D1 and survivin level." (PMID 31949487, 2020). "Prior work in ovarian cancer has suggested that AMPK activation causes degradation of cyclin D1 through a pathway involving glycogen synthase kinase 3β." (PMID 30875375, 2019). "We recently uncovered that SMARCA4 loss in an ovarian cancer subtype causes cyclin D1 deficiency leading to susceptibility to CDK4/6 inhibition." (PMID 30718506, 2019). "This is a logical result of MAPK–ERK pathway activation, as both C‐myc and Cyclin‐D1 are oncogenic elements implicated in ovarian cancer development." (PMID 27374312, 2016). "This study found that the increased mRNA and protein expression levels of cyclin D1 and cyclin E caused by Lewis y overexpression were consistent with the decreased proportion of G1 phase in ovarian cancer cells resulting from Lewis y overexpression." (PMID 22312289, 2012). "In epithelial ovarian cancer, overexpression of cyclin D1 has been associated with decreased survival in patients." (PMID 21152316, 2010). "Furthermore, MYC, EGFR, CCND1 exhibited close association with chemotherapeutic response to platinum and showed a high expression in ovarian cancer tissues and platinum-resistant ovarian cancer cells." (PMID 35739532, 2022). "Preoperative evaluation of CCND1 gene expression in ovarian cancer patients may benefit the assessment of risk and prognosis, provide a new basis for CCND1 gene as a novel target for tumor therapy, and also pave the way for clinical treatment." (PMID 34806539, 2021). "Preoperative evaluation of CCND1 gene expression in ovarian cancer patients may benefit the assessment of risk and prognosis." (PMID 34806539, 2021). "Overexpression of Ccnd1 is strongly correlated to decreased progression free survival and loss of Cdkn2a through mutation or hypermethylation has also been shown in human ovarian carcinomas." (PMID 24672774, 2014). "There are no studies on the clinical significance of nEGFR expression in CRC, except for those referring to the breast, oropharyngeal squamous and ovarian cancer, with the expression associated with worse prognosis, increased proliferation and cyclin-D1 expression." (PMID 22050898, 2011). "In our investigation, Kirenol decreased ovarian cancer cells' expression of CCND1 and phosphorylation of PI3K, AKT, and RB." (PMID 38415456, 2025). "ANXA114‐26 promotes apoptosis and reduces drug resistance in ovarian cancer cells through the FPR/Cyclin D1/NF‐ĸBp65 pathway." (PMID 39712859, 2025). "We also examined the changes in the expression of Cyclin D1 and NF‐ĸBp65 in ovarian cancer cells treated with ANXA114‐26 in combination with cisplatin." (PMID 39712859, 2025). "Previous research has demonstrated that cyclin D1 is a crucial regulator of cell cycle progression in ovarian cancer cells and that the degradation of cyclin D1 was enough to trigger G1 cell cycle arrest." (PMID 39941011, 2025).
ovarian carcinoma (continued). "It indicated that ANXA114‐26 had multiple effect on the ovarian cancer cell proliferation, drug resistance, and downstream protein NF‐ĸBp65 through Cyclin D1." (PMID 39712859, 2025). "The epidermal growth factor receptor (EGFR), which is overexpressed in up to 60% of ovarian cancers, upregulates expression of c-Myc and cyclin D1, promoting both aerobic glycolysis and cell cycle progression." (PMID 39639170, 2025). "Our results suggest that ANXA114‐26 reduces ovarian cancer cell proliferation and drug resistance by decreasing the expression of Cyclin D1." (PMID 39712859, 2025). "Currently, a large number of studies have shown that overexpression of CCND1 leads to chemoresistance in various malignant tumors, such as testicular, BC, prostate and ovarian cancer." (PMID 39739897, 2024). "Their results proved that upregulation of miRNA-576-3p can increase cisplatin chemosensitivity of ovarian cancer cells by inhibiting PD-L1 and cyclin D1." (PMID 39195233, 2024). "Early studies have shown that human TCEAL7 can inhibit Cyclin D1 expression induced by c-Myc in ovarian epithelial cells and negatively regulate NF-κB signaling through repressing p65 transcriptional activity in ovarian cancer cells." (PMID 37047236, 2023). "Our data also showed that HMGB3 suppression reduces the expression of major downstream target genes of the MAPK/ERK signaling pathway, including ETS-1, CCND1, and c-Myc, which have key roles in ovarian cancer occurrence and development." (PMID 37328851, 2023). "Cypermethrin induced the growth of the ovarian cancer cell line BG-1 and up-regulated cyclin D1 expression." (PMID 36908412, 2023). "Although the correlation of CCND1 to ovarian cancer chemoresistance is rarely mentioned, CCND1 is well-known as a cell cycle regulatory protein that participates in the regulation of cell proliferation and apoptosis in tumors." (PMID 35739532, 2022). "A previous in vitro study showed that overexpression of mortalin (a stress response-related glucose-regulated protein) mediated ovarian cancer cell (A2780) proliferation by inducing abnormal expression of cyclin-B1 and cyclin-D1." (PMID 35334562, 2022). "After 48 h of bexarotene treatment, the levels of CDK4, CDK6, Cyclin D1, and phospho-RB decreased in both ovarian cancer cell lines." (PMID 35778597, 2022). "MYC, EGFR, and CCND1 expressed at higher protein levels in ovarian cancer patients than in normal ovarian tissues." (PMID 35739532, 2022). "We further demonstrated that METTL14 inhibited the expression of TROAP via the m6A RNA modification in ovarian cancer cells, which also inhibited cell proliferation by suppress cyclin D1, survivin, and p-AKT." (PMID 35251990, 2022). "PKM2 overexpression promotes the proliferation and growth of ovarian cancer (OC) cells by increasing the expression of recombinant cyclin D1 (CCND1)." (PMID 36276846, 2022). "CCND1 is up-regulated in human epithelial ovarian cancer tissues and cells, and its abnormal expression is related to the malignancy of epithelial ovarian cancer." (PMID 35739532, 2022). "Correlation analysis was performed based on the expression of MYC, EGFR, and CCND1 in the TCGA-ovarian cancer dataset." (PMID 35739532, 2022). "Combined with results of PPI analyses and TCGA database, MYC, EGFR, and CCND1 were determined to be the key genes correlated with the chemoresistance affected by CAFs in ovarian cancer." (PMID 35739532, 2022). "Results exhibited positive correlations of MYC, EGFR, and CCND1 with overall survival of ovarian cancer patients after chemotherapy." (PMID 35739532, 2022). "In ovarian cancer, the inhibition of CCND1 expression by cisplatin can reduce cell proliferation and increase cell apoptosis." (PMID 36118276, 2022).
ovarian carcinoma (continued). "Consistently, in this study, exogenously expressed of HK2 also promoted cell growth in human ovarian cancer cells by accelerating cell cycle progression (up-regulated the expression of cell cycle-related factors, like cyclin A1, cyclin D1 and cyclin E1)." (PMID 35953860, 2022). "Masamha and Benbrook have previously observed that Cyclin D1 degradation is sufficient to induce G1 cell cycle in ovarian cancer cells." (PMID 36113340, 2022). "Cyclin D1 degradation has been reported to occur through the AMPK/GSK3β signaling axis through the proteasome pathway in ovarian cancer cells." (PMID 35411000, 2022). "Our results showed that BTG2 expression regulated ovarian cancer cell proliferation via G1/S phase cell cycle arrest by regulating Cyclin D1, CDK4, p-AKT, and p-ERK expression." (PMID 34485119, 2021). "The effect of silencing CCND1 gene on the apoptosis of ovarian cancer cells was detected by flow cytometry." (PMID 34806539, 2021). "Kaplan-Meier Plotter database showed that the overall survival and progression-free survival of ovarian cancer patients with high CCND1 expression were significantly shorter than those of patients with low CCND1 expression (P < 0.05)." (PMID 34806539, 2021). "Therefore, CCND1 may be closely associated with the prognosis of ovarian cancer patients." (PMID 34806539, 2021). "The survival of ovarian cancer patients was analyzed based on the Kaplan-Meier Plotter database, and the correlations between CCND1 and overall survival (OS) and progression-free survival (PFS) of ovarian cancer patients were retrieved online." (PMID 34806539, 2021). "The expression of CCND1 in advanced ovarian cancer tissues is higher than that in early ones, and the prognosis of patients with high CCND1 expression is poor." (PMID 34806539, 2021). "Here, we found that the overexpressed ACSM3 blocked the expression of Integrin β1 and p-AKT, leading to the down-regulation of cyclin D1, c-Myc, Vimentin and the up-regulation of E-cadherin in ovarian cancer cells." (PMID 33869039, 2021). "The expressions of CCND1 gene in normal ovarian epithelial cells and SKOV3 ovarian cancer cells were detected by RT-PCR, and the relative expression of CCND1 gene was calculated." (PMID 34806539, 2021). "Adib Ovarian, Bonome Ovarian and Hendrix Ovarian microarrays revealed that the expression of CCND1 gene in ovarian cancer tissue was significantly higher than that in normal ovarian tissue (P < 0.05)." (PMID 34806539, 2021). "Although the role of CCND1 in ovarian cancer has been well described, its synergistic effect with PSMC2 has not been investigated." (PMID 34294689, 2021). "By studying the Adib Ovarian, Bonome Ovarian and Hendrix Ovarian microarrays, it was found that the expression of Cyclin D1 gene in ovarian cancer tissue was significantly higher than that in normal ovarian tissue (P < 0.05)." (PMID 34806539, 2021). "The expression of CCND1 gene in ovarian cancer and the effect of silencing its expression on cancer cells were analyzed by cell experiments." (PMID 34806539, 2021). "We aimed to analyze the expression of Cyclin D1 (CCND1) gene in ovarian cancer and the influence of silencing its expression on ovarian cancer cells based on the Oncomine database." (PMID 34806539, 2021). "Thereby motivated, we herein aimed to investigate the expression and mechanism of CCND1 gene in ovarian cancer in order to clarify the mechanism for the occurrence and development of ovarian cancer at the level of molecular biology." (PMID 34806539, 2021). "The expression of CCND1 gene in ovarian cancer was analyzed by utilizing the relevant information in different tumors and Oncomine database." (PMID 34806539, 2021). "In ovarian cancer cells, HOTAIR positively stimulates CCND1 and CCND2 genes, whose upregulation is associated with tumor progression." (PMID 33540611, 2021).